TRPM7 (transient receptor potential cation channel subfamily M member 7)
Diseases named in the same sentence as TRPM7 in open-access papers (continued):
Sharing a sentence is not in itself a finding about the gene and the disease.
pancreatic adenocarcinoma (continued). "In the majority of pancreatic adenocarcinoma specimens examined, TRPM7 is expressed at either moderate-level or high-level." (PMID 25770184, 2015). "We have previously reported that TRPM7 is essential for maintaining Mg2+-dependent proliferation and preventing replicative senescence in pancreatic adenocarcinoma cells." (PMID 25770184, 2015). "There is a statistically significant correlation between the expression levels of TRPM7 in pancreatic adenocarcinoma and the size and stages of tumors." (PMID 25770184, 2015). "Consistent with the immunohistochemical data, in the pancreatic adenocarcinoma cell line with elevated expression of TRPM7, targeted silencing of TRPM7 impairs the cancer cells ability of invasion." (PMID 25770184, 2015). "Anti-TRPM7 immunoreactivity in pancreatic adenocarcinoma significantly correlates with the size and stages of tumors." (PMID 25770184, 2015). "Over-expression of TRPM7 in pancreatic adenocarcinoma positively correlates with increased tumor size and advanced tumor stages." (PMID 25770184, 2015). "In a previous report, we provided evidence that the levels of TRPM7 mRNA are relatively high in human pancreatic adenocarcinoma cell lines including BxPC-3, PANC-1, MIA PaCa-2, PL45, and Capan-1." (PMID 25770184, 2015). "The novel finding of RNA interference-mediated silencing of TRPM7 induces replicative senescence in pancreatic adenocarcinoma cell lines suggests a therapeutic approach complementary to conventional agents that target apoptosis." (PMID 25079291, 2014). "This is supported by the finding that aberrant over-expression of TRPM7 in pancreatic adenocarcinoma positively correlates with tumor size and stage." (PMID 25079291, 2014). "By translating the developmental studies of Trpm7 in zebrafish to humans, we have found the previously unidentified role of TRPM7 in pancreatic adenocarcinoma." (PMID 24278689, 2012). "As a potential therapeutic approach in pancreatic adenocarcinoma, we can target the TRPM7 and TRPM8 ion channels via chemical and/or genetic modulation of their channel activities and their associated signaling pathways." (PMID 24278689, 2012). "Taken together, TRPM7 is required for Mg2+-dependent cellular proliferation in the developing exocrine pancreas and in pancreatic adenocarcinoma through modulation of the cell cycle regulators." (PMID 24278689, 2012). "Importantly, in the case of human pathological pancreatic adenocarcinoma, TRPM7 and TRPM8 are overexpressed and are necessary biomarkers for cancer cell proliferation." (PMID 35573736, 2022). "TRPM7 is expressed at a moderate to high level in the majority of pancreatic adenocarcinoma cases." (PMID 25770184, 2015). "Importantly, the expression levels of TRPM7 in pancreatic adenocarcinoma positively correlate with the tumor size and stage." (PMID 25770184, 2015). "These suggest that mechanisms other than gene amplification may account for the aberrantly elevated expression of TRPM7 in pancreatic adenocarcinoma." (PMID 25770184, 2015). "Expression of TRPM7 is increased in a panel of human pancreatic adenocarcinoma cells and tissues." (PMID 25770184, 2015). "Similarly, another pancreatic adenocarcinoma cell line (MIA PaCa-2) expressing anti-TRPM7 shRNA exhibited reduced ability of cell invasion (N.S.Y., personal observation)." (PMID 25770184, 2015). "Notably, anti-TRPM7 immunoreactivity in pancreatic adenocarcinoma is accentuated towards the plasma membrane." (PMID 25770184, 2015). "In human pancreatic adenocarcinoma tissues, TRPM7 protein is aberrantly overexpressed." (PMID 24278689, 2012). "Similarly, the mRNA levels of TRPM7 are elevated in the majority of human pancreatic adenocarcinoma cell lines being examined." (PMID 24278689, 2012). "In addition, TRPM7 is overexpressed in breast and pancreatic adenocarcinomas." (PMID 23533657, 2013).
pancreatic adenocarcinoma (continued). "We hypothesize that aberrantly up-regulated expression of TRPM7 in pancreatic adenocarcinoma contributes to the uncontrolled proliferation and invasion of the cancer cells by facilitating cell cycle progression and cell migration and by preventing replicative senescence." (PMID 24278689, 2012). "The relatively high anti-TRPM7 immunoreactivity in chronic pancreatitis, PanINs, IPMN, and pancreatic adenocarcinoma implies a contributory role of TRPM7 channels in pancreatic carcinogenesis." (PMID 25770184, 2015). "With identification of the role of TRPM7 in pancreatic development and cancer, we examined the expression of the other TRPM subfamily of ion channels in a panel of human pancreatic adenocarcinoma cell lines." (PMID 24278689, 2012). "The aberrant over-expression and proliferative roles of the TRPM7 and TRPM8 ion channels in pancreatic adenocarcinoma suggest a unique opportunity of their development as clinical biomarkers and therapeutic targets." (PMID 24278689, 2012). "The novel findings of Trpm7 ion channel in the growth control of exocrine pancreas in zebrafish prompted discovery of the aberrant expression as well as the proliferative and migratory roles of TRPM7 and TRPM8 channels in human pancreatic adenocarcinoma." (PMID 24278689, 2012). "In addition to being activated by their activators, TRPM2, TRPM4, and TRPM5 can also be triggered by the influx of Ca2+ to participate in membrane depolarization, and TRPM2, TRPM7, and TRPM8 are involved in the progression of pancreatic adenocarcinoma." (PMID 35573736, 2022). "Elevated expression of TRPM7 in metastatic tumors (n = 16) as compared to that in non-metastatic pancreatic adenocarcinoma (stages I, II, and III combined, n = 266) was present but statistically marginal (P = 0.1)." (PMID 25770184, 2015). "Moreover, we have demonstrated the novel roles of the human orthologue TRPM7 and its sub-family member TRPM8 in pancreatic adenocarcinoma." (PMID 24278689, 2012). "Moreover, anti-TRPM7 immunoreactivity tends to be stronger in pancreatic adenocarcinoma that metastasizes than non-metastatic tumors." (PMID 25770184, 2015). "In attempt to test the hypothesis that deregulated expression and/or activities of developmental regulators contributes to carcinogenesis, we have discovered that TRPM7 and TRPM8 are aberrantly overexpressed in pancreatic adenocarcinoma and required for proliferation of the cancer cells." (PMID 24278689, 2012). "In our working model, activation of TRPM7 by various stimuli modulates intracellular Mg2+ and/or Ca2+ levels and interact with the epidermal growth factors (EGF-) induced signaling pathways, resulting in cell cycle progression, cell survival, and cell migration in pancreatic adenocarcinoma." (PMID 24278689, 2012). "Therefore, immense potential exists for TRPM7 and TRPM8 channels to be developed as clinically useful biomarkers and valid therapeutic targets with the hope of accomplishing personalized therapy for patients with pancreatic adenocarcinoma and other malignant diseases." (PMID 24278689, 2012).
ischemic stroke (8 papers, 2015 to 2024). A stroke disorder caused by obstruction of blood flow to the brain, due to thrombotic (local blood clot formation) or embolic (due to a blood clot or other material traveling from another site) event. "Compared to TRPM4, the detrimental effects of TRPM7 in ischemic stroke have been extensively studied since 2003." (PMID 35159300, 2022). "Several in vivo studies demonstrated that TRPM7 function contributes to ischemic stroke, although the involvement of its channel and kinase activity in the regulation of Zn2+ homeostasis under ischemic conditions is still under investigation." (PMID 31652790, 2019). "TRPM7 is ubiquitously and highly expressed in brain and plays an important role in the pathophysiology of CNS like ischemic stroke." (PMID 25799367, 2015). "Most previous studies concentrated on the functions of TRPM7 channel in neurons under different pathophysiological status such as ischemic stroke, oxygen-glucose deprivation (OGD), oxidative stress, hypoxia and inflammation." (PMID 25799367, 2015). "In the vascular system, inhibition of TRPM7 reduces calcification in VSMCs induced by high inorganic phosphates; disruption of platelet TRPM7 kinase activity protects mice from arterial thrombosis and ischemic stroke." (PMID 39425532, 2024). "In addition to TRPM2, TRPM4 and TRPM7 are also highly expressed in the brain, and were found to aggravate the brain injury following ischemic stroke." (PMID 35159300, 2022). "The unique feature of TRPM7 among all TRPM channels is its high permeability to zinc, and zinc toxicity has been well documented as an important cause of neuronal death after ischemic stroke." (PMID 35159300, 2022). "Similarly, it has been argued that TRPM7 channels provide an important pathway for neuronal Zn2+ uptake and subsequent cell death in the pathophysiological context of ischemic stroke." (PMID 25106481, 2015). "Consequently, deletion of TRPM7 kinase activity in mice significantly reduces SOCE in platelets, and protected mice from ischemic brain insults, indicating that the increased kinase function, rather than its channel function of TRPM7, plays an important role in ischemic stroke." (PMID 31652790, 2019).
pancreatic ductal adenocarcinoma (8 papers, 2015 to 2024). An infiltrating adenocarcinoma that arises from the epithelial cells of the pancreas. "TRPM7 expression correlated positively to a poorly differentiated status and reduced patient survival in pancreatic ductal adenocarcinoma." (PMID 38255793, 2024). "TRPM7 channels are expressed in pancreatic stellate cells involved in the development and progression of pancreatic ductal adenocarcinoma." (PMID 38255793, 2024). "Another group showed that TRPM7 mRNA and protein are overexpressed in pancreatic ductal adenocarcinoma compared to healthy pancreatic tissue, and TRPM7 staining intensity is inversely correlated with patients’ survival." (PMID 32182937, 2020). "TRPM7 is also overexpressed in pancreatic ductal adenocarcinoma, in which higher TRPM7 levels in primary tumors correlate with higher levels of lymph node metastasis." (PMID 31275168, 2019). "Furthermore, TRPM7 has a 13-fold higher expression in pancreatic ductal adenocarcinoma (PDAC) compared with non-cancer tissue, with TRPM7 expression correlated with tumour progression and a poor survival rate." (PMID 32825277, 2020). "Both TRPM7 and TRPM8 proteins are absent in normal pancreatic ducts, but are present in a subset of pancreatic ductal adenocarcinoma patients, where TRPM8 expression heralds adverse outcomes." (PMID 37240443, 2023).
Sepsis (8 papers, 2018 to 2025). Sepsis is defined as life-threatening organ dysfunction caused by a dysregulated host response to infection. "Pearson correlation coefficient showed that HULC expression was positively associated with the expression of TRPM7 in serum of sepsis patients." (PMID 32484206, 2020). "TRPM7 associates with increased mortality and enhanced risk of death during sepsis." (PMID 36869357, 2023). "TRPM7 ion channel activity and α-kinase function are required by DIC-mediated sepsis-induced organ dysfunction and its expression are associated with increased mortality during sepsis." (PMID 36869357, 2023). "A significant inverse correlation between miR-204-5p expression and TRPM7 expression in serum of sepsis patients was analyzed by Pearson correlation coefficient (P<0.0001)." (PMID 32484206, 2020). "TRPM7 ion channel has been reported to be a key protein in the regulation of inflammatory response during sepsis, and TRPM7 was also involved in LPS-induced transformation of endothelial cells into activated fibroblasts." (PMID 32484206, 2020). "Our data indicated that HULC potentiated in sepsis patients and accompanied with decreased miR-204-5p expression and enhanced TRPM7 expression." (PMID 32484206, 2020). "In conclusion, HULC and TRPM7 expression levels were up-regulated in sepsis patients and LPS-induced HUVECs, while miR-204-5p was down-regulated." (PMID 32484206, 2020). "The recovery experiments proved that LPS induced the development of sepsis by regulating HULC/miR-204-5p/TRPM7 axis." (PMID 32484206, 2020). "HULC and TRPM7 were increased and accompanied with decreased miR-204-5p expression in serum of sepsis patients." (PMID 32484206, 2020). "HULC, microRNA-204-5p (miR-204-5p) and TRPM7 expressions in serum of sepsis patients and human umbilical vein endothelial cells (HUVECs) were examined by quantitative real-time polymerase chain reaction (qRT-PCR)." (PMID 32484206, 2020). "The data revealed that TRPM7 was strikingly fortified in mRNA and protein levels in serum of sepsis patients compared with that in healthy controls (P<0.0001, P<0.0001)." (PMID 32484206, 2020). "LPS promotes sepsis progression by activating the HULC/miR-204-5p/TRPM7 axis in HUVECs." (PMID 39067063, 2025). "Taken together, our results show that circ-Gatad1 promoted LPS-induced HK2 cell injury via regulating the miR-22-3p/TRPM7 signaling pathway, suggesting that circ-Gatad1 knockdown might be a potential pathway for alleviating sepsis-induced AKI." (PMID 38443846, 2024). "What’s more, Ivanka found that sepsis-induced DIC is facilitated by TRPM7 within ECs." (PMID 39267971, 2024). "Our study demonstrates that sepsis-induced DIC is mediated by TRPM7 in ECs." (PMID 36869357, 2023). "Therefore, TRPM7 emerges as a novel target for treating DIC in SSPs since its suppression promotes increased survival and decreased risk of death during sepsis." (PMID 36869357, 2023). "Also, it has been shown that TRPM6 and TRPM7 modulation at the same time modulate the response to diseases like sepsis." (PMID 33291725, 2020). "We then examined the expression of TRPM7 in serum of patients with sepsis." (PMID 32484206, 2020). "The ion channel activity of TRPM7 and the functioning of α-kinase are crucial for the organ dysfunction resulting from DIC in sepsis, with their presence correlating with elevated mortality rates in septic conditions." (PMID 39267971, 2024). "Taken together, the prothrombotic phenotype induced by endotoxemia requires TRPM7 activity, which promotes DIC-mediated organ dysfunction and death during sepsis." (PMID 36869357, 2023). "TRPM7 mediates DIC progression, and its activity is required in DIC-induced organ dysfunction during sepsis." (PMID 36869357, 2023). "A septic rat model treated with salvianolic B showed that sepsis-induced ALI was reduced due to decreased levels of TRMP6 and TRPM7 mRNA in lung tissue, potentially linking TRPM7 to neutrophil migration and infiltration." (PMID 30126133, 2018).
Sepsis (continued). "TRPM7 expression and levels of TNF-α, IL-6 and IL-1β are increased in the serum of patients with sepsis diagnosis and those patients with sepsis and a high expression of TRPM7 have a decreased survival rate in comparison to patients with a low expression of TRPM7." (PMID 33291725, 2020). "Besides, we did not investigate the role of HULC/miR-204-5p/TRPM7 axis in sepsis in vivo models." (PMID 32484206, 2020). "As an ion channel, TRPM7 was closely related with intracellular signaling, yet we did not explore whether HULC/miR-204-5p/TRPM7 axis affected sepsis development via regulating some signaling pathways." (PMID 32484206, 2020).
Obesity (7 papers, 2020 to 2025). Accumulation of substantial excess body fat. "Our data indicate that TAK1, downstream of TRPM7, is the pivotal nodal point for obesity-associated inflammation." (PMID 36717580, 2023). "TRPM7 is also recognized as a metabolism-associated channel that plays a crucial role in obesity-mediated hypertension." (PMID 36717580, 2023). "Thus, the expression and activity of TRPM7 appeared to be positively associated with obesity in mice." (PMID 36717580, 2023). "Moreover, TRPM7 channel participates in obesity-associated disorders." (PMID 36717580, 2023). "In this study, TRPM7 was observed to be an immunometabolic regulator in fat pads that links obesity to inflammation." (PMID 36717580, 2023). "To evaluate the function of TRPM7 in adipose tissue, we explored TRPM7 expression in adipose tissue in obesity." (PMID 36717580, 2023). "Further, oral administration of TRPM7 inhibitor FTY720 on obese mice protected against obesity and insulin resistance." (PMID 36717580, 2023). "Our results demonstrate TRPM7 as a factor in the development of adipose inflammation that regulates insulin sensitivity in obesity." (PMID 36717580, 2023). "Adipocyte-specific elimination of TRPM7 maintains insulin sensitivity and protects mice from diet-induced obesity and adipose inflammation." (PMID 36717580, 2023). "Given that obesity is closely associated with glucose intolerance and insulin resistance, we assessed glucose homeostasis in the CD- and HFD-fed control and TRPM7 ATKO mice." (PMID 36717580, 2023). "This indicates that TRPM7 is the major source of pro-inflammatory and pro-obesity signals promoting metabolic disorder development." (PMID 36717580, 2023). "These insights open a line of investigation for a better understanding of adipose inflammation and how TRPM7 modulates glucose homeostasis in obesity." (PMID 36717580, 2023). "Because adipocyte hypertrophy occurs in obesity, it is possible that this cellular distention activates TRPM7 and further leads to the changes in gene programs." (PMID 33195411, 2020). "Transient receptor potential melastatin-like 7 (TRPM7) is known to be related to inflammation; however, the role of TRPM7 in adipocyte phenotype and function in obesity remains unclear." (PMID 36717580, 2023). "These rescue experiments, which aim to reverse the improvement in obesity-linked metabolic disorder by upregulating TAK1, reflect a requirement of TAK1 function in the development of obesity and inflammation states regulated by TRPM7." (PMID 36717580, 2023). "Additionally, obese mice treated with TRPM7 inhibitor are protected against obesity and insulin resistance." (PMID 36717580, 2023). "In addition, we provided evidence to show that adipocyte TRPM7 was upregulated primarily in adipocytes, and specific deletion of TRPM7 in adipocytes was sufficient to attenuate HFD-induced obesity, insulin resistance, and inflammation." (PMID 36717580, 2023). "In obesity, the observed upregulation of TRPM7 in adipose tissue may be in turn elicited by inflammation." (PMID 36717580, 2023). "The dynamics of TRPM7 expression led us to investigate whether TRPM7 regulates metabolic dysfunction in adipose tissues and the development of obesity." (PMID 36717580, 2023). "Notably, weight loss in the HFD-fed ATKO mice was not related to the changes in food intake compared to the HFD-fed Flox mice, suggesting that the resistance of adipocyte-specific TRPM7 knockout mice to diet-induced obesity was attributed to higher catabolic rates." (PMID 36717580, 2023). "However, the pathophysiological role of TRPM7 in obesity-induced adipose inflammation remains unclear." (PMID 36717580, 2023). "Our finding revealed that FTY720 administration in obese mice could protect against obesity and insulin resistance via changes in adipose tissue inflammation, suggesting that pharmacological inhibition of TRPM7 using FTY720 may also benefit patients with obesity and others with insulin resistance." (PMID 36717580, 2023).